SELP (selectin P)
Description:
Ca(2+)-dependent receptor for myeloid cells that binds to carbohydrates on neutrophils and monocytes. Mediates the interaction of activated endothelial cells or platelets with leukocytes. The ligand recognized is sialyl-Lewis X. Mediates rapid rolling of leukocyte rolling over vascular surfaces during the initial steps in inflammation through interaction with SELPLG. Mediates cell-cell interactions and cell adhesion via the interaction with integrin alpha-IIb/beta3 (ITGA2B:ITGB3) and integrin alpha-V/beta-3 (ITGAV:ITGB3).
Synonyms: GMP-140; LECAM3; PADGEM; CD62P; GRMP; CD62; PSEL; GMP140
Tractability: Small molecule: a drug acting on it is in phase 2 or 3 trials; a structure with a bound ligand is known; a high-quality ligand is known; it belongs to a druggable protein family. Antibody: an approved drug acts on it; UniProt places it where antibodies can reach, with high confidence; its Gene Ontology location is reachable by antibodies, with high confidence; UniProt predicts a signal peptide or a membrane-spanning region. PROTAC: its protein half-life has been measured; a small molecule that binds it is known.
Target class: Adhesion
Gene: Protein-coding gene on chromosome 1 (169,588,421 to 169,630,193, reverse strand). Ensembl gene ENSG00000174175.
Subcellular location: Cell membrane
Pathways (Reactome):
Hemostasis: Cell surface interactions at the vascular wall; Platelet degranulation
Gene Ontology:
Molecular function: calcium ion binding; fucose binding; heparin binding; integrin binding; lipopolysaccharide binding; oligosaccharide binding; protein binding; sialic acid binding; signaling receptor activity; glycosphingolipid binding; calcium-dependent protein binding
Biological process: calcium-dependent cell-cell adhesion; cell-cell adhesion; leukocyte cell-cell adhesion; leukocyte tethering or rolling; positive regulation of phosphatidylinositol 3-kinase/protein kinase B signal transduction; regulation of integrin activation; cell adhesion; defense response to Gram-negative bacterium; heterophilic cell-cell adhesion; positive regulation of leukocyte tethering or rolling; positive regulation of platelet activation; response to cytokine; response to lipopolysaccharide
Cellular component: external side of plasma membrane; extracellular region; plasma membrane; platelet alpha granule membrane; platelet dense granule membrane; membrane
Genetic constraint (gnomAD): Loss-of-function variants: 76 observed, 94.64 expected, observed/expected ratio (o/e) 0.8, 90% interval 0.67 to 0.97. The upper end of that interval is the gene's LOEUF score, 0.97, which puts it in group 4 of 6, group 1 being the genes least tolerant of losing a copy. Missense variants: 933 observed, 980.46 expected, observed/expected ratio (o/e) 0.95, 90% interval 0.9 to 1. Synonymous variants: 364 observed, 355.5 expected, observed/expected ratio (o/e) 1.02, 90% interval 0.94 to 1.12.
Homologues: Orthologues: chimpanzee SELP (98% identical), macaque SELP (95% identical), dog SELP (77% identical), rabbit SELP (71% identical), rat Selp (69% identical), mouse Selp (67% identical), guinea pig SELP (67% identical), pig SELP (57% identical). Paralogues in human: SELE (34% identical), CSMD1 (24% identical), CSMD3 (24% identical), CSMD2 (24% identical), SVEP1 (23% identical), SELL (20% identical), CR1 (18% identical), CR2 (17% identical), CFH (13% identical), C4BPA (13% identical), CR1L (11% identical), SEZ6L2 (11% identical), and 27 more.
Diseases named in the same sentence as SELP in open-access papers:
SELP is named in the same sentence as 376 diseases in open-access papers, as found by Europe PMC text mining. Sharing a sentence is not in itself a finding about the gene and the disease. The quoted sentences say what the papers report.
COVID-19 (134 papers, 2020 to 2026). A disease caused by infection with severe acute respiratory syndrome coronavirus 2. "Our work highlighted an increased expression of genes related to the endomembrane system, such as RAB1B, RAB24, RAB32, JAK3, and SELP, in severe COVID-19 patients’ blood samples." (PMID 38262689, 2024). "The P-selectin plasma levels were reduced in the presented COVID-19 and post-COVID-19 female patients vs. the corresponding male patients." (PMID 37896963, 2023). "A recent study performed within the Italian GEN-COVID cohort identified an association between the homozygous state of the functional polymorphism p.(Asp603Asn) (rs6127) in P-selectin gene (SELP) and COVID-19 severity in a subcohort of 513 male subjects." (PMID 35618891, 2022). "MKs were found to express the ligand SELP, suggesting interactions between MKs and LDNs, and an active role for MKs in the pathogenesis of severe COVID-19." (PMID 34721400, 2021). "We also observed a trend that convalescent COVID-19 patients who recovered from severe symptoms had the highest number of SELP+ CECs, although insignificant." (PMID 33752798, 2021). "We conclude that hypercoagulation and the cytokine storm in severe COVID-19 are linked through the spike-CD42b interaction that activates platelets, the CD40L-CD40 and the P selectin–PSGL-1 interactions that bind them to monocytes, and the strong induction of IL-1β in the monocytes." (PMID 34964720, 2022). "Coronavirus disease-COVID-19 and lipid and atherosclerosis connect with TRAF3, TLR2, SELP and CASP1 deregulated molecules." (PMID 36553678, 2022).
atherosclerosis (121 papers, 2007 to 2025). A disease characterized by the build-up of fatty material and calcium deposition in the arterial wall resulting in partial or complete occlusion of the arterial lumen. "It has been discovered that interaction between FIB and P-selectin pitches in the progression of atherosclerosis, and enhanced FIB level is a potential risk factor for atherosclerotic biomarkers." (PMID 40099273, 2025). "The role of sP-selectin in atherosclerosis development and its association with the risk of venous thromboembolism is supported by studies of SELP polymorphisms and research in animal models." (PMID 28646244, 2017). "The relevance of SELP in RA and other diseases is underlined by the finding of increased soluble SELP levels for many diseases, including atherosclerosis, in which soluble SELP is derived mostly from endothelial cells, and RA." (PMID 25147926, 2014). "Similarly, SELP (selectin-P) deficiency, one of the hepatic key regulators that in our study was found to be upregulated and linked to atherosclerosis signaling via TNFSF11, reduces atherosclerosis in combined P-selectin/ApoE knock-out mice vs. ApoE single knock-out mice." (PMID 35897797, 2022). "The common mechanisms shared in both are linked with atherosclerosis signaling and inflammatory response with at least the following target genes: Tnfrsf12a, Pla2g2f, Il1f9, Col1a1, Col1a2, and Col3a1 in brain, while Tnfrsf12a, SELP, SELE, IL6, and IL1A in myocardium." (PMID 29681850, 2018). "Increased ROS production can activate the platelets and help to participate in the signaling event of atherosclerosis in diabetes by forming aggregates with monocytes through P-selectin–PSGL-1 interactions." (PMID 35127948, 2021). "Knock-in mice with elevated plasma levels of soluble SELP showed several abnormalities related to atherosclerosis and cerebrovascular complications." (PMID 29958078, 2018). "Selectins and the genes encoding selectin (e.g., P-selectin (SELP) and P-selectin glycoprotein ligand-1 (SELPG)) may be explored as biomarkers for atherosclerosis and other CVDs." (PMID 40724991, 2025). "SELP might be involved in developing atherosclerosis and TALDO1 in obstructive coronary artery disease." (PMID 40921935, 2025). "Taken together, these results suggest that FDT may inhibit atherosclerosis by targeting SELP and CCL2." (PMID 38794213, 2024). "Through a combination of UFLC-TOF-MS, network pharmacology, and experimental validation, we found that FDT attenuated atherosclerosis and exerted anti-inflammatory effects by suppressing SELP and CCL2 gene expression, contributing to monocyte adhesion and migration." (PMID 38794213, 2024). "In conditions such as atherosclerosis, where AT-III, Fbg, and SELP interact, several studies have shown that SELP is negatively connected with the levels of several coagulation factors such as AT-III and Fbg." (PMID 36769725, 2023). "Ten key regulated genes (including Pla2g2f, Il1f9, Col1a1, Col1a2, and Col3a1 in the brain, while SELP, SELE, IL6, and IL1A in the myocardium, and Tnfrsf12a in both) are correlative with atherosclerosis signaling and inflammatory response." (PMID 29681850, 2018). "Pathway “Lipid and Atherosclerosis” and related genes, for example, LYN, SELP, OLR1." (PMID 40621499, 2025). "In a mouse model of atherosclerosis, investigating the promotion of atherosclerosis by an adoptive transfer of P-selectin positive or negative bone marrow platelets, in addition to endothelial P-selectin, platelet P-selectin contributed to lesion formation." (PMID 25152735, 2014). "Targeting SELP and CCL2 may be a potential intervention for atherosclerosis therapy." (PMID 38794213, 2024). "Therefore, SELP and CCL2 were selected as the active targets for FDT against atherosclerosis." (PMID 38794213, 2024).
atherosclerosis (continued). "Indeed, both platelet and endothelial P-selectin contributed to lesion formation in a mouse model of atherosclerosis that was based on the adoptive transfer of P-selectin positive or negative platelets." (PMID 25784879, 2015).
endothelial dysfunction (86 papers, 2010 to 2026). In vascular diseases, endothelial dysfunction is a systemic pathological state of the endothelium (the inner lining of blood vessels) and can be broadly defined as an imbalance between vasodilating and vasoconstricting substances produced by (or acting on) the endothelium. "It is very well known that pathological levels (both decreased and increased levels) of fibrin(ogen), D-dimer, VWF and P-selectin play crucial roles in abnormal coagulation and endothelial dysfunction." (PMID 32708334, 2020). "Afterward, activation of the intrinsic and extrinsic coagulation pathways determines an overproduction of thrombin, inducing thrombotic inflammation effects and endothelial dysfunction, promoting the expression of P-selectin proteins in endothelial cells, and activating neutrophils and platelets." (PMID 40005354, 2025). "As a cell adhesion molecule, P-selectin plays a role in endothelial dysfunction." (PMID 22852092, 2012).
thrombosis (81 papers, 2007 to 2026). "We examined the link between each prognosis risk factor and SELP levels separately to better understand the connection between SELP levels and prognostic risk factors (history of thrombosis, age, and white blood cell count)." (PMID 36769725, 2023). "We aimed to investigate whether P-selectin polymorphisms are associated with thrombosis in patients with antiphospholipid syndrome (APS)." (PMID 25541651, 2014). "In this study, we aim to investigate whether P-selectin polymorphisms are associated with thrombosis in patients with APS." (PMID 25541651, 2014). "Among them, mutations in ABCA13, FLT1, NRP1, SWAP70 and SLC15A4 are strongly associated with immunity or proliferation, whereas mutations in VWF, SELP and EPHB2 are associated mainly with thrombosis." (PMID 39671267, 2024). "A positive correlation between age and SELP expression has been found in diseases related to hyperlipidemia and thrombosis, and the same was found in the present study in ET patients." (PMID 36769725, 2023). "In a recent study, RNA sequencing in granulocytes of PV patients documented higher expression levels of F3, SELP, VEGFA, and SLC2A1, that were directly correlated with JAK2 expression and JAK2V617F allele burden in patients with a history of thrombosis." (PMID 34897288, 2021). "Our discovery that peripheral blood leukocyte counts, age, and a history of thrombosis were all related to serum SELP levels in ET patients further supports these findings and suggests a possible mechanism by which serum SELP levels are related to prognosis in ET patients." (PMID 36769725, 2023). "At the same time, as this study is a clinical study, the relationship between SELP and various factors and thrombosis is only a speculative result, which needs to be confirmed by further laboratory studies." (PMID 36769725, 2023). "The results were a higher resting level of P-selectin positive platelets in cocaine users compared to healthy controls which the authors concluded could mediate a process of thrombosis." (PMID 17880705, 2007). "Additionally, P-selectin polymorphisms were detected in patients with thrombosis, but not always together with high sP-selectin levels." (PMID 25541651, 2014).
Sepsis (68 papers, 2009 to 2025). Sepsis is defined as life-threatening organ dysfunction caused by a dysregulated host response to infection. "The metabolism of selenium is disturbed during sepsis, leading to a reduction in serum selenium levels caused by the diminished synthesis of Selenoprotein P [SelP], the selenoprotein that plays a crucial role in selenium transport." (PMID 40867920, 2025). "The modulatory effect of miR-26b on SELP expression was confirmed in MEG-01 cells under these inflammatory conditions using a specific miRNA mimic, suggesting that sepsis-reduced miR-26b caused increased SELP expression in sepsis." (PMID 32013235, 2020). "SELP mRNA level was elevated in sepsis, especially in platelets with increased mean platelet volume, causing higher P-selectin expression." (PMID 32013235, 2020). "We next investigated whether changes in platelet miR-26b expression were associated with the severity of sepsis and the clinical outcome in the presence of elevated platelet P-selectin positivity." (PMID 32013235, 2020). "Thus, enhanced SELP expression in platelets might contribute to a higher risk for cellular interactions and might represent a new therapeutic target in those with sepsis." (PMID 32013235, 2020). "In a LPS-induced sepsis model, platelet miR-26b is significantly downregulated, which contributes to elevated P-selectin (SELP) expression of MKs and platelets, and augments platelet activation." (PMID 35757325, 2022). "Based on a recent animal model with peritoneal sepsis, mice showed increased P-selectin positivity at 48 h as a part of the prothrombotic phenotype of platelets developed in sepsis." (PMID 32013235, 2020). "In the entire sepsis group consisting of 21 patients showing an increased level of platelet activation, we validated the expression of platelet miR-26b that regulates SELP expression." (PMID 32013235, 2020). "Inflammatory mediators and cell adhesion molecules including ICAM-1, VCAM-1, P-selectin, and E-selectin participate in inflammatory sepsis induced lung injury." (PMID 25120287, 2014). "sepsis was associated with the C11_Plate cluster, and ESAM, HBG2, MMRN1, PF4V1, SAMD14, SELP, and TGFB1I1 may be important in this context." (PMID 37919720, 2023). "Based on these current results, we proposed a signaling axis in MKs and platelets upon sepsis when lower Dicer level resulted in decreased miR-26b with elevated target SELP expression that could contribute to the elevated level of platelet activation status." (PMID 32013235, 2020). "Importantly, SELP mRNA targeted by miR-26b was upregulated in sepsis (p < 0.001) relative to healthy platelets." (PMID 32013235, 2020). "Due to the increased SELP expression in patient platelets after the development of sepsis, we wondered whether P-selectin at protein level could be also detected at a higher quantity in platelets." (PMID 32013235, 2020). "Finally, a gene ontology (GO) analysis was performed to study the role of upregulated SELP expression in MK function in sepsis." (PMID 32013235, 2020). "For example, during the cytokine-induced changes as observed in sepsis, IL-1β (which was part of the cytomix cocktail to stimulate the mouse ECs in our study) is released and adhesion molecules (such as VCAM-1 and SELP) are upregulated from human ECs during inflammation." (PMID 35955534, 2022). "Gene entities shared between sepsis and severe sepsis response hubs are; TDRD9 – LIN7A, GPR84 – ENTPD7, PYCT1A and ZDHHC19, CD177 – DDAH2 and RGL4, SLC16A3 – DENND3 and MBD6, MYL9 – CMTM5, ITGB3, ITGA2B, NRGN, SELP and TREML1." (PMID 32318053, 2020). "CMTM5, SELP, and TREML1 were also observed in pediatric resolved SIRS, in addition to ALOX12 (arachidonate 12-lipoxygenase, 12S type), which was also seen in pediatric sepsis." (PMID 32318053, 2020). "Although SELP expression did not significantly correlate with the outcome of sepsis in these patients, increased MPV values also predicted disease prognosis, as reported by others in sepsis with pneumonia." (PMID 32013235, 2020).
Stroke (68 papers, 2009 to 2026). Sudden impairment of blood flow to a part of the brain due to occlusion or rupture of an artery to the brain. "This network of interactions included three genes, BMP6, TGFBR2, TGFBR3 with a functional role in the TGF-beta pathway and one gene (SELP) associated with stroke in the general population." (PMID 20401335, 2009). "The presence among the risk factors of genes already associated with stroke in the general population, such as SELP, suggests that some genetic factors predisposing to stroke may be shared by both SCA patients and stroke victims in general." (PMID 20401335, 2009). "P-selectin plasma levels were lower in women than in men at day 1 (79.1 ± 66.7 vs. 48.9 ± 15.4 in pg/mL) but not on day 4 (113.6 ± 82.6 vs. 83.5 ± 46.4 in pg/mL) after stroke." (PMID 34858141, 2021). "Interestingly, a lower number of P-selectin-positive microvesicles has been previously observed in patients after stroke without recurrent vascular event during the observation period." (PMID 32370146, 2020).
diabetes (63 papers, 2007 to 2026). "In type 2 diabetes mellitus, decreased platelet miR-26b has been associated with elevated SELP expression, resulting in higher platelet reactivity." (PMID 32013235, 2020). "Selenoprotein P (SelP), a selenium-supply protein, is hypothesized to raise the risk of diabetes by promoting insulin resistance and dysregulating glucose metabolism." (PMID 37275636, 2023). "In a clinical trial study, salvianolic acid A inhibited the plasma level of SELP in patients with type 2 diabetes mellitus." (PMID 38794213, 2024).
breast carcinoma (45 papers, 2011 to 2025). "We observed that individual lung-derived E-, L-, or P-selectin play a functional role in the migration of TN breast cancer cells." (PMID 34829810, 2021). "Selectin-P (SELP) was found to be important in organ-specific metastatic dissemination of breast cancer." (PMID 33573289, 2021).
myocardial infarction (39 papers, 2004 to 2025). Gross necrosis of the myocardium, as a result of interruption of the blood supply to the area, as in coronary thrombosis. "Conversely, studies such as the Etude Cas-Témoin de l’Infarctus du Myocarde (ECTIM) have shown a protective effect of the G allele against myocardial infarction, proposing SELP rs6136 as a polymorphic variant with a population-dependent role." (PMID 39768338, 2024).
Thrombocytopenia (34 papers, 2012 to 2026). A reduction in the number of circulating thrombocytes. "Elevated levels of M-CSF have been attributed to severe cases of P. falciparum malaria, where platelet destruction and the release of P-selectin plays a role in thrombocytopaenia associated with severe disease." (PMID 22554058, 2012).